BRCA1 (BRCA1 DNA repair associated)
Diseases named in the same sentence as BRCA1 in open-access papers (continued):
Sharing a sentence is not in itself a finding about the gene and the disease.
tumor (continued). "Metformin-induced restriction of mitochondrial biosynthetic capacity was sufficient to impair the tumor-initiating capacity of BRCA1 one-hit cells in mammosphere assays." (PMID 27259235, 2016). "A subset of FA proteins includes the well‐characterised RAD51 recombinase, as well as the tumour suppressors BRCA1 and BRCA2, which are directly involved in the homologous recombination (HR) pathway of double‐strand break (DSB) repair." (PMID 27037238, 2016). "It was observed that the BRCA1- mutated cell lines were enriched for ALDH1+ cells in both normal-like tumor forming (MDA-MB-436) and basal-like tumor forming cell lines." (PMID 27229859, 2016). "The importance of the Abraxas-BRCA1 interaction in tumor suppression is also suggested by identification of an Abraxas mutation in tumor in the phenylalanine residue of the pSPxF motif (F409C)." (PMID 26778126, 2016). "However, the use of a tumor sample for molecular analysis and further mutational analysis of the entire coding sequence of both BRCA1 and BRCA2 may significantly increase the total number of patients who may potentially benefit from targeted therapies with PARP inhibitors." (PMID 27167707, 2016). "It has been well characterized that BRCA1 functions as a tumor suppressor for many cases of hereditary breast and ovarian cancer." (PMID 27754413, 2016). "Acquired chemotherapy resistance is mainly associated with the inactivation of tumour suppressors such as RB1, NF1, RAD51B and PTEN, germline BRCA1 or BRCA2 mutations, loss of BRCA1 promoter methylation, and overexpression of the drug efflux pump MDR12." (PMID 27833130, 2016). "The tumor suppressor BRCA1, for example, is critically involved in DSB repair, favoring the failsafe HR over the more error-prone NHEJ pathway." (PMID 26871287, 2016). "There were 38 cases with high BRCA1 protein expression and 81 with low expression for whom blood and tumour DNA methylation were available." (PMID 27463681, 2016). "DHX9 has several interacting partners that are directly involved in DNA repair, the most prominent being the tumor suppressor BRCA1." (PMID 26625211, 2016). "Similar phenomena in terms of creating a “tumor-friendly” environment in stroma tissue have recently been observed concerning the tumor suppressor gene BRCA1." (PMID 27590516, 2016). "The aim of this study is to investigate the effect of PARG deficiency on BRCA1- and/or PTEN-deficient tumour cells." (PMID 27375368, 2016). "We observed a flipped distribution of ID4 transcript compared to BRCA1 abundance in the two tumor classes." (PMID 27077368, 2016). "In particular, despite its clinical importance as a tumor suppressor that has been recognized for decades, the reason why BRCA1 is so important for aborting tumorigenic events remains enigmatic." (PMID 27446204, 2016). "Here, we examine site-specific and spatiotemporal alteration in DNA methylation at a target region in BRCA1 gene promoter, a model tumour suppressor gene." (PMID 27356740, 2016). "Our results indicate that metformin can limit the enhanced tumor-initiating capacity of mutant BRCA1 one-hit cells by starving them of the biosynthetic intermediates required for an efficient anabolic cell growth and survival." (PMID 27259235, 2016). "Biallelic BRCA1/2 inactivation was also considered, because tumor cells with monoallelic BRCA inactivation are unresponsive to PARPi." (PMID 27907908, 2016). "Among them, LOH in tumor was identified in 11 (61.1%) BRCA1 carriers and 13 (59.1%) BRCA2 carriers, respectively." (PMID 27257965, 2016).
tumor (continued). "The expression of PARP1, γH2AX, BRCA1, and BRCA2 were significantly associated with each other and were associated with higher tumor stage and presence of distant metastasis." (PMID 27643881, 2016). "BRCA1 is a tumor suppression gene whose protein product is involved in the maintenance of DNA homeostasis via multiple mechanisms such as DNA repair, transcription, cell cycle, and apoptosis." (PMID 27410681, 2016). "We have focused on obtaining a comprehensive dataset consisting of methylation levels for blood and tumour DNA, BRCA1 protein expression, hormone receptor status, and morphological and clinico-pathological features." (PMID 27463681, 2016). "Yet another tumour suppressor, BRCA1, reciprocally promotes end resection and homologous recombination (HR)." (PMID 27655732, 2016). "In summary, we have identified a BRCA1-deficient, NFκB-driven biology that predicts good outcome in TNBC due to the promotion of a favourable tumour microenvironment where immune targeting of the tumours is more efficient." (PMID 26943587, 2016). "BRCA1 participates in tumor suppression and its ubiquitin ligase activity has a significant role in this tumor suppression." (PMID 27754413, 2016). "We also observed that the germline BRCA1 P/LP variants have a stronger association with aggressive phenotypes, including triple-negative, tumor grade III, and advanced tumor stage M1." (PMID 27257965, 2016). "BRCA1 tumours often display high numbers of infiltrating lymphocytes both intratumoural and in the surrounding stroma." (PMID 26943587, 2016). "In vitro studies suggest that cells with BRCA1 CpG island methylation are also sensitive to PARP1 inhibitors and tumour BRCA1 promoter methylation predicts response to platinum based chemotherapy agents and PARP inhibitors." (PMID 27463681, 2016). "Using these cells we have studied the in vivo association of BRCA1 with Ubc9, expression of Ubc9 in these BRCA1 mutant TNBC and HGSOC cell lines and tumor tissues." (PMID 28164176, 2016). "Herein, we used dCas9 fused to the TET1 catalytic domain (TET1CD) and co-treated with various combinations of sgRNA to demonstrate targeted epigenetic editing namely demethylation at the promoter of BRCA1, a model tumour suppressor gene." (PMID 27356740, 2016). "In preclinical models AG014699 (i.v. rucaparib compound) inhibits tumour growth in not only mutant BRCA1/2 models, but also in those with non-BRCA mutant-deficient HR, such as deficient XRCC3 and epigenetically silenced BRCA1." (PMID 27002934, 2016). "Tumor subtype profile by ER and HER-2 expression were very similar to previously published data for both the wild-type and BRCA-1 mutated groups." (PMID 27023391, 2016). "In the ovary, a tumor suppressor gene BRCA1 has been shown to have ubiquitin E3 ligase activity and has been reported to be expressed in granulosa cells." (PMID 27548147, 2016). "Reproductive history has been reported to alter this risk, suggesting a relationship between ovarian hormone signaling and BRCA1-related tumor development." (PMID 27246982, 2016). "NGS was used for BRCA1/2 sequencing of FFPE tumor samples (average sequencing depth: >5700×; mean uniformity: 91.1%)." (PMID 27907908, 2016). "This patient also has a somatic frameshift mutation in BRCA1 (p.K1160Lfs*47) at 32% in the NGS data (in 50% tumor), suggesting this allele is present in the tumor in a hemizygous state." (PMID 27626691, 2016). "While PhenDC drastically reduced viability of Brca1−/− mouse tumor-derived cells, its toxicity against BRCA2-deficient V-C8 cells was rather modest." (PMID 26748828, 2016). "We also confirmed the findings of a recent report regarding the feasibility of using FFPE tumor samples for NGS analysis of alterations in the BRCA1/2 genes." (PMID 27907908, 2016). "BRCA1 knockdown significantly extended survival of the tumour-bearing mice, thereby confirming the supporting role of BRCA1 in GBM growth and maintenance." (PMID 27845331, 2016).
tumor (continued). "Our study shows that although some tumour cells display slight sensitivity to PARG deficiency, this sensitivity cannot be correlated to BRCA1- or PTEN- deficiency." (PMID 27375368, 2016). "The study of patients with TNBC who carry the BRCA-1 and BRCA-2 mutation is one analysis pathway, as these tumours are sensitive to PARP (polyadenosine diphosphate ribose polymerase 1) inhibitors like Olaparib, which penetrates the BBB." (PMID 27170832, 2016). "A previous study indicated that the characteristics of tumor-infiltrating lymphocytes (TIL) are influenced by the disruption of BRCA1, which is a well-known tumor suppressor gene of ovarian cancer." (PMID 27483433, 2016). "In conclusion, BARD1β displays oncogenic activities through negatively affecting the tumor suppressor functions of BRCA1." (PMID 27197561, 2016). "In summary, our study reveals a phosphorylation-dependent mechanism in Abraxas-mediated recruitment and accumulation of BRCA1 at DNA damage sites, deepening our understanding of BRCA1 and Abraxas tumor suppressor function and related cellular signaling." (PMID 26778126, 2016). "The levels of BRCA1 promoter methylation at 9 of the 11 CpG sites in blood DNA were found to correlate with methylation at the corresponding sites in matched tumour DNA in the 170 cases for which both were available." (PMID 27463681, 2016). "BRCA1 is an important tumor suppressor, which plays an essential role in maintaining genomic stability and integrity." (PMID 27403158, 2016). "FOXO3 methylation levels were significantly higher in BRCA1-mutated tumours compared with BRCA2, BRCAx (non-BRCA1/2) and non-BRCA1-mutated (BRCA2/x) tumours." (PMID 27043660, 2016). "The tumor suppressor BRCA1 plays a pivotal role in maintaining genomic stability and tumor suppression." (PMID 26848770, 2016). "Substantial crosstalk between the two pathways has recently been unravelled, in that key HR proteins such as the RAD51 recombinase and the tumour suppressors BRCA1 and BRCA2 also play important roles in ICL repair." (PMID 27037238, 2016). "BRCA1 and BRCA2 appear to behave as tumor suppressor genes, and mutations in either of these genes have been found throughout the entire coding region and at splice sites." (PMID 27242959, 2016). "The IR-induced phosphorylation of Abraxas and the subsequent stabilization of BRCA1-BRCT dimerization are likely to comprise an important mechanism for accumulation of BRCA1 to DNA-damaged chromatin and BRCA1 mediated tumor suppression." (PMID 26778126, 2016). "ER and HER-2 expression are among the most important clinicopathologic tumor characteristics, and the rates of receptor expression status in the DEABM closely match those observed in both wild type and BRCA-1 mutated populations." (PMID 27023391, 2016). "The tumor suppressor BRCA1 plays a key role in HR by promoting end resection, which enables loading of the RAD51 recombinase and initiation of HR-mediated repair." (PMID 26748828, 2016). "MEC cells of IFDUC1, derived from a tumor characterized as ER+/PR+/Her2+ and non-BRCA1 hereditary were both CD44+ and CD24+." (PMID 26968831, 2016). "The BRCA1 promoter methylation levels were generally higher in tumour DNA compared to normal breast tissue DNA, most significantly at -51, -21, -19 and +19 (p<0.03)." (PMID 27463681, 2016).
tumor (continued). "As a result, chromosomal instability (mutations, translocations) increases and when it exceeds the ability of cellular DNA damage response mechanisms to repair the damage, BRCA1-incompetent tumor cells are directed on the pathway to apoptosis." (PMID 27626685, 2016). "Predicted pathogenic germline mutations in BRCA1 and BRCA2 were identified in 1.36% and 1.64% of the cohort, respectively, and 2.22% of tumours harboured pathogenic CHEK2 germline mutations." (PMID 27161491, 2016). "BRCA1 and BRCA2 are mutated in 22% of tumours, owing to a combination of germline and somatic mutations." (PMID 27833130, 2016). "This disturbing trend suggest that chemotherapy, e.g., cisplatin generates BRCA1-IRIS overexpressing cells in the other 50% of patients with tumor expressing low level of the protein." (PMID 27489859, 2016). "In the reproducibility experiments, three different samples (blood, FFPE tumour and snap-frozen tumour) with known germline exonic BRCA1 or BRCA2 gene deletions or duplications were prepared in triplicates by three different operators." (PMID 26569395, 2015). "We systematically reviewed important differences in design between the studies and assessed their methodological rigor using a specially developed scoring-system aiming to give the best evidence regarding the prognosis of BRCA1- and BRCA2-associated tumours." (PMID 25816289, 2015). "Given that BRCA1 protein has a tumor-suppressive role and is considered to be a “chromosome custodian”, we delved into the relationships between Pit-1 and BRCA1." (PMID 25992773, 2015). "It appears that the tumor inhibitory effect of KSR1 is BRCA1-dependent as shown by in vitro 3D-matrigel and soft-agar assays." (PMID 26425651, 2015). "Although BRCA1 knockout provokes embryonic lethality in mice, conditional knockout of BRCA1 in breast tissue leads to tumor development after a long latency." (PMID 26379698, 2015). "Hypermethylation was associated with advanced tumor stage for ABCC6 (P = 0.050), BRCA1 (P = 0.032), CDH1 (P = 0.004), GDF15 (P = 0.005), HSPA2 (P = 0.000), RASSF1A (P = 0.003), TSHB1 (P = 0.018), and TMEFF2 (P = 0.002)." (PMID 25613404, 2015). "Recently, BRCA1 and VDR association has been demonstrated to activated genes involved in anti-tumor effects of vitamin D, and that a complete knockdown of BRCA1 abolishes the effects of vitamin D analogues." (PMID 25992773, 2015). "Kaplan-Meier analysis showed a trend in shorter OS for patients with RRM2, TS, and ERCC1, BRCA1 overexpressed tumours." (PMID 26663950, 2015). "Much like olaparib, BMN 673 has been shown to cause single-agent synthetic lethality in BRCA1/2- and PTEN-deficient cell lines, with potent antitumour activity in animal models of tumours harbouring mutations in DNA repair pathways." (PMID 26610585, 2015). "The most striking observation was that the staining for both mRNA and protein is heterogeneous across the tumor: some areas strongly expressed BRCA1 and others only faintly, as illustrated in the two magnified subzones." (PMID 26490435, 2015). "BRCA1, being a tumour suppressor and a regulator of DNA-damage repair, has a reciprocal role to CCNE1 whose overactivation accelerates cell divisions and confers replication stress and genomic instability." (PMID 26427375, 2015). "Taken together, these data suggest that BRCA1-IRIS overexpression is important for TNBC tumor maintenance." (PMID 25583261, 2015). "On average, we observed that BRCA-1 promoter methylation (M/U ratio) was increased ~6.6-fold in TBNC compared to non-tumor breast tissue." (PMID 26715507, 2015). "The C-terminal domain binds to N-terminal RING domain of BRCA1 and regulates BRCA1 mediated tumor suppressor function." (PMID 26680512, 2015). "BRCA1 was evaluated in this manner because it is a known tumour suppressor gene, whose gene promoter contains a PPRE." (PMID 25889730, 2015).
tumor (continued). "It has also been found that treatment with a retroviral vector expressing wild-type BRCA1 significantly inhibited tumor growth and increased survival in mice with established MCF-7 tumors." (PMID 25992773, 2015). "BRCA1 is a nuclear tumor suppressor critical for DSBs and inter-strand cross-links by the HR mechanism." (PMID 26501335, 2015). "In vivo we show with three different tumor models, two of which are BRCA1 mutant, that there is a difference in the number of DSBs observed depending on the daily dose of olaparib." (PMID 25984718, 2015). "BRCA1 is a tumor suppressor gene located on chromosome 17q21 that has been intensively investigated as participating in the repair of cisplatin-induced DNA double-strand breaks." (PMID 25912308, 2015). "Here, we show that the tumour suppressor BRCA1, together with its interacting partner CtIP, both acting in end resection, also promotes end-joining of uncapped telomeres." (PMID 25582120, 2015). "BRCA1 gene acts as tumor suppressor and plays a role in maintenance of genomic stability through DNA damage recognition and repair." (PMID 26426992, 2015). "Here, we present extensive evidence showing a paclitaxel-resistance-promoting role for BRCA1-IRIS overexpression in TNBC tumor cells, in vitro and in vivo." (PMID 25583261, 2015). "Considering the tumor-suppressive role of BRCA1, any perturbation in this regulatory function is likely to have an effect on BRCA1-mediated tumor development." (PMID 26392359, 2015). "The tumour suppressor BRCA1 functions in homologous recombination repair to activate CtIP through ubiquitylation, which mediates its recruitment to sites of damage in cell cycle-regulated manner." (PMID 25582120, 2015). "The result seemed to display a trend that BRCA1 hypermethylation tumors tended to be the smaller tumor size." (PMID 25789047, 2015). "Bound to BRCA1, BARD1 is essential for BRCA1’s E3 ubiquitin ligase and tumor suppressor activity in DNA repair and cell cycle control." (PMID 26415510, 2015). "Among these differentially regulated pathways, the BRCA1-mediated tumor suppression and G1/S cell cycle checkpoint (FDR-adjusted P-value< 0.05, respectively) were the two most significantly changed canonical pathways thus identified." (PMID 26623723, 2015). "Significant, tumour-specific loss of heterozygosity occurs in nine genes (ATM, BAP1, BRCA1/2, BRIP1, FANCM, PALB2 and RAD51C/D)." (PMID 26689913, 2015). "This study aimed to establish a correlation among the BRCA1-related molecular parameters, tumor characteristics and clinical follow-up of patients to find new prognostic factors." (PMID 26490435, 2015). "Many of these BRCA1 properties and, in particular, those that protect genome integrity, probably contribute to its tumor suppressing function (Silver and Livingston, 2012, Tutt and Ashworth, 2002)." (PMID 25699710, 2015). "This evidence strongly suggests that therapy-induced activation of BRCA1-IRIS pathway promotes tumor cell survival through autocrine signaling loops." (PMID 25583261, 2015). "Hereditary defects in genes for HR factors such as BRCA1 and BRCA2 lead to cancer predisposition syndromes and tumours that are reliant on alternative repair pathways for survival." (PMID 25833379, 2015).